SOAT2 (sterol O-acyltransferase 2)
Description:
Catalyzes the formation of fatty acid-cholesterol esters, which are less soluble in membranes than cholesterol. Plays a role in lipoprotein assembly and dietary cholesterol absorption. Utilizes oleoyl-CoA ((9Z)- octadecenoyl-CoA) and linolenoyl-CoA ((9Z,12Z,15Z)-octadecatrienoyl-CoA) as substrates. May provide cholesteryl esters for lipoprotein secretion from hepatocytes and intestinal mucosa. [Isoform 2]: Has lower enzymatic activity compared to isoform 1. [Isoform 3]: Has lower enzymatic activity compared to isoform 1.
Synonyms: ACACT2; ACAT2; ARGP2
Tractability: Small molecule: a drug acting on it is in phase 2 or 3 trials; a structure with a bound ligand is known; a high-quality ligand is known; it belongs to a druggable protein family. Antibody: UniProt predicts a signal peptide or a membrane-spanning region. PROTAC: UniProt records ubiquitination sites on it; a small molecule that binds it is known.
Target class: Enzyme; Transferase
Chemical probes: CHEMBL2334539
Gene: Protein-coding gene on chromosome 12 (53,103,461 to 53,124,538, forward strand). Ensembl gene ENSG00000167780.
Subcellular location: Endoplasmic reticulum membrane
Pathways (Reactome):
Transport of small molecules: LDL clearance
Gene Ontology:
Molecular function: cholesterol binding; cholesterol O-acyltransferase activity; fatty-acyl-CoA binding; protein binding; sterol O-acyltransferase activity; acyltransferase activity
Biological process: cholesterol efflux; cholesterol metabolic process; lipid transport; very-low-density lipoprotein particle assembly; cholesterol homeostasis; intestinal cholesterol absorption; low-density lipoprotein particle clearance; macrophage derived foam cell differentiation; positive regulation of intestinal cholesterol absorption
Cellular component: brush border; endoplasmic reticulum; endoplasmic reticulum membrane; membrane
Genetic constraint (gnomAD): Loss-of-function variants: 87 observed, 74.09 expected, observed/expected ratio (o/e) 1.17, 90% interval 0.99 to 1.4. The upper end of that interval is the gene's LOEUF score, 1.4, which puts it in group 5 of 6, group 1 being the genes least tolerant of losing a copy. Missense variants: 686 observed, 679.01 expected, observed/expected ratio (o/e) 1.01, 90% interval 0.95 to 1.08. Synonymous variants: 285 observed, 273.32 expected, observed/expected ratio (o/e) 1.04, 90% interval 0.95 to 1.15.
Homologues: Orthologues: chimpanzee SOAT2 (99% identical), macaque SOAT2 (96% identical), pig SOAT2 (85% identical), dog SOAT2 (85% identical), rabbit SOAT2 (84% identical), mouse Soat2 (82% identical), rat Soat2 (82% identical), guinea pig SOAT2 (57% identical), tropical clawed frog soat2 (55% identical), zebrafish soat2 (49% identical), Drosophila melanogaster CG8112 (31% identical), Caenorhabditis elegans mboa-1 (28% identical). Paralogues in human: SOAT1 (47% identical), DGAT1 (23% identical).
Diseases named in the same sentence as SOAT2 in open-access papers:
SOAT2 is named in the same sentence as 32 diseases in open-access papers, as found by Europe PMC text mining. Sharing a sentence is not in itself a finding about the gene and the disease. The quoted sentences say what the papers report.
atherosclerosis (9 papers, 2009 to 2024). A disease characterized by the build-up of fatty material and calcium deposition in the arterial wall resulting in partial or complete occlusion of the arterial lumen. "Farese and colleagues then examined the contribution of Soat2-derived CE to atherosclerosis by crossing Soat2−/− mice with Apoe-deficient mice." (PMID 34436484, 2021). "Similar to targeted gene deletion, inhibition of function or disruption of expression of SOAT2 by pharmacological means causes major alterations in cholesterol homeostasis and atherosclerosis development." (PMID 24901470, 2014). "Treatment of Apoe-/- mice with the SOAT2 selective inhibitor pyripyropene A caused reductions in cholesterol absorption, plasma VLDLc and LDLc concentration, cholesteryl oleate content of apoB-containing lipoproteins, and atherosclerosis progression." (PMID 24901470, 2014). "At 30 weeks of age, the Soat2−/−Apoe−/− mice fed with a chow diet had smaller atherosclerosis lesions in all aortic regions (arch, thorax, and abdomen) than the Soat2+/+ Apoe−/− controls." (PMID 34436484, 2021). "The enzyme sterol O-acyltransferases (Soat1 and Soat2), which catalyze the synthesis of CE from free cholesterol, are regarded as a potential target for atherosclerosis and hypercholesterolemia." (PMID 33790973, 2021). "Researchers now understand that SOAT has two isozymes, SOAT1 and SOAT2, with distinct functions in the human body, and that selective inhibition of SOAT2 is responsible for the prevention of atherosclerosis and fatty liver disease." (PMID 32640743, 2020). "SOAT2 was shown to play a critical role in delaying the development of atherosclerosis." (PMID 35498757, 2022). "Recent studies indicated that hepatic or intestinal SOAT2 might play a more important role in hypercholesterolemia or atherosclerosis." (PMID 27936201, 2016). "In addition, genes Soat1 and Soat2 are known to encode ACAT1 and ACAT2 enzymes in catalyzing the formation of cholesteryl esters, an important process during atherosclerosis formation." (PMID 19835623, 2009). "Accordingly, the studies on SOAT2-specific inhibitors, such as PPPA, revealed the potential of this class of compounds to treat hypercholesterolemia and atherosclerosis." (PMID 27936201, 2016).
Obesity (5 papers, 2015 to 2025). Accumulation of substantial excess body fat. "SOAT2 has been implicated in cholesterol metabolism and obesity." (PMID 40428823, 2025). "SOAT2 is a major regulator of cholesterol metabolism and absorption in the small intestine and liver of mice on a high-cholesterol and high-fat diet and impaired cholesterol absorption has been linked to high BMI and obesity through a yet unknown mechanism." (PMID 26674805, 2015). "This nanoparticle system was composed of PLGA‐block‐PEG and chitosan specifically delivering Soat2 siRNAs into small intestines in mice, effectively inhibit intestinal lipid uptake and resolving obesity." (PMID 39297413, 2024). "We found that intestine‐specific SOAT2 knockout (Soat2I‐KO) mice was capable to prevent the development of dietary induced obesity due to reduced intestinal lipid absorption." (PMID 39297413, 2024). "Our study developed PLGA‐b‐PEG and CS coupled Soat2 siRNA nanoparticle system targeting inhibition of intestinal SOAT2 to control dietary fatty acid intake so as to prevent the development of dietary induced obesity." (PMID 39297413, 2024). "This work demonstrates a potential modulatory function of intestinal SOAT2 on lipid uptake highlighting the therapeutic effect on obesity by targeting intestinal SOAT2, exhibiting promising translational relevance in the siRNA therapeutic–based treatment for obesity." (PMID 39297413, 2024). "Treatment with Soat2 siRNA/CS‐PLGA nanoparticles was capable to inhibit SOAT2 in enterocytes, which would be adequate to prevent the development of high‐fat diet induced obesity." (PMID 39297413, 2024).
hepatocellular carcinoma (4 papers, 2020 to 2025). A malignant tumor that arises from hepatocytes. "Increased activity and expression of sterol O-acyltransferases (SOATs) have been observed in human colon carcinoma and hepatocellular carcinoma (HCC), and the inhibition of SOAT2 is shown to suppress HCC tumor cell growth." (PMID 39863145, 2025). "Thus, SOAT2 might partially compensate the lack of SOAT1 activity in Huh7 cells, explaining the lesser effects on ZIKV replication in hepatoma cells compared to Hmc3 and 1321N1 cells." (PMID 39237833, 2024).
fatty liver disease (3 papers, 2020 to 2024). A reversible condition wherein large vacuoles of triglyceride fat accumulate in liver cells via the process of steatosis. "Marked suppression of two enzymes, SOAT2 and GK, is assumed to play an important role in increasing lipid levels in the affected liver, bringing about hepatic steatosis." (PMID 38419509, 2024).
prostate carcinoma (3 papers, 2022 to 2025). A carcinoma that arises from epithelial cells of the prostate gland. "MYH6 and SOAT2 may be associated with the progression of prostate cancer." (PMID 36694223, 2023). "Both SOAT1 and SOAT2 staining was localized to the cytoplasmic region of prostate cancer cells consistent with their known localization at the endoplasmic reticulum." (PMID 34326474, 2022). "Protein expression of SOAT1 and SOAT2 has not been examined in prostate cancer tissue." (PMID 34326474, 2022).
breast carcinoma (2 papers, 2023). "Survival and Cox analyses of all the DEGs confirmed CCL1 and MYH6 were independent protective factors and IFNK and SOAT2 were independent risk factors for basal-like breast cancer (95%CI: 1.06–2.5, p = 0.026)." (PMID 36694223, 2023). "On the contrary, IFNK, MYH6, and SOAT2 have rarely been reported in association with breast cancer." (PMID 36694223, 2023). "We further constructed a four-gene signature comprising CCL1, IFNK, MYH6, and SOAT2 genes, which shows a promising predictive value for basal-like breast cancer and may be related to the underlying Th1/Th2 balance regulation mechanism, which is worthy of further study." (PMID 36694223, 2023). "CCL1, MYH6, IFNK, and SOAT2 have an independent prognostic value of survival outcome and might be novel markers in basal-like breast cancer." (PMID 36694223, 2023).
colon carcinoma (2 papers, 2021 to 2025). "Besides, in colon cancers, much lower SOAT2 was expressed than SOAT1." (PMID 33637695, 2021).
acute pancreatitis (1 paper, 2025). An acute inflammatory process that leads to necrosis of the pancreatic parenchyma. "Sterol o‐acyltransferase 2 (SOAT2) has been reported to aggravate acute pancreatitis, however, the underlying mechanism remains to be elucidated." (PMID 39588852, 2025). "Therefore, we constructed the ELAVL1/SOAT2/NRF2/HO‐1 axis to elucidate the mechanism underlying SOAT2's regulation in the progression of acute pancreatitis, with the goal of identifying potential therapeutic targets for this disorder." (PMID 39588852, 2025). "A recent paper revealed that SOAT2 inhibitor alleviated acute pancreatitis, however, the molecular mechanism underlying how SOAT2 regulates acute pancreatitis remains unclear." (PMID 39588852, 2025). "Understanding the mechanism of SOAT2 in acute pancreatitis can provide valuable insights into potential targets for intervention and the development of novel therapeutic approaches for managing this metabolic disorder." (PMID 39588852, 2025). "In this study, the focus is on analyzing the role and mechanism of SOAT2 in acute pancreatitis using AR42J cells." (PMID 39588852, 2025). "A recent study has highlighted that SOAT2 expression is upregulated in a mouse model of acute pancreatitis." (PMID 39588852, 2025). "Taken together, ELAVL1‐dependent SOAT2 aggravated pancreatic exocrine cell injury by inactivating the NRF2/HO‐1 pathway in acute pancreatitis." (PMID 39588852, 2025). "By investigating how SOAT2 impacts the pathogenesis of acute pancreatitis at the cellular level, researchers aim to elucidate its potential contribution to the disease pathology and identify new avenues for therapeutic intervention." (PMID 39588852, 2025). "Thus, SOAT2 contributed to the progression of acute pancreatitis by inhibiting pancreatic exocrine cell proliferation and promoting apoptosis, inflammatory response, and ferroptosis." (PMID 39588852, 2025).
aortic atherosclerosis (1 paper, 2014). A atherosclerosis that involves the aorta. "By using an antisense oligonucleotide targeting Soat2 mRNA (SOAT2 ASO), SOAT2 expression was knocked down in a liver-specific manner resulting in decreased LDL cholesteryl oleate and diminished aortic atherosclerosis development." (PMID 24901470, 2014).
pancreatitis (1 paper, 2025). Inflammation of the pancreas. "In conclusion, ELAVL1‐dependent SOAT2 exacerbated pancreatic exocrine cell injury by inactivating the NRF2/HO‐1 pathway in pancreatitis." (PMID 39588852, 2025).
sarcopenia (1 paper, 2025). Progressive decline in muscle mass due to aging which results in decreased functional capacity of muscles. "Their statistical analyses revealed that SOAT2 variants, including rs2272303, rs11170413, and rs2272302, may play roles in sarcopenia risk." (PMID 40428823, 2025).
steatosis (1 paper, 2021). Increased lipid within the cytoplasm of cells. "This study suggests that hepatic ApoJ may activate sterol O-acyltransferase 2 to supply cholesteryl-ester for lipid loads, thus presenting ApoJ as a promising target for treating stress-induced steatosis." (PMID 33980978, 2021). "Taken together, hepatic ApoJ might activate SOAT2 to supply cholesteryl-ester for lipid loads, thus providing a therapeutic target of stress-induced steatosis." (PMID 33980978, 2021). "In conclusion, hepatic ApoJ might interact with SOAT2 through IDR region, facilitating Chol esterification for LD deposition and lipoprotein loading under steatosis inducers." (PMID 33980978, 2021).
testicular germ cell tumor (1 paper, 2021). A germ cell tumor arising from the testis. "We further examined mRNA expressions of SOAT1 vs. SOAT2 in liver hepatocellular carcinoma (LIHC) and testicular germ cell tumors (TGCT) tissues; the result revealed that SOAT1 expression remained higher than SOAT2." (PMID 34052835, 2021).
ZIKV infection (1 paper, 2025). "ZIKV infection significantly upregulated SOAT2 mRNA levels, while SOAT1 mRNA levels showed less pronounced increase that occurred only at 24 hours post infection." (PMID 41306517, 2025). "ZIKV infection induces SOAT1 and SOAT2, increasing the amount of cholesteryl esters." (PMID 41306517, 2025).
tumor (6 papers, 2015 to 2025). "Our group discovered that SOAT1 expression is highly upregulated in tumor tissues from GBM patients, while SOAT2 is undetectable in tumor tissues." (PMID 36009491, 2022). "Regarding cholesterol metabolism, SOAT2 participates in tumor metabolic reprogramming." (PMID 40533802, 2025). "And the copy number variation of SOAT1 was elevated in tumor tissues compared with non-tumor tissues, while SOAT2 had no significance using the Oncomine database." (PMID 34052835, 2021). "After adjustment for age, preoperative PSA, tumor stage, Gleason score, resection status, lymph node involvement and year of surgery, high SOAT1 but not SOAT2 expression was associated with shorter BCR free survival with a hazard ratio of 2.40 (95% CI 1.57–3.68, p < 0.001)." (PMID 34326474, 2022).
cancer (4 papers, 2020 to 2024). A tumor composed of atypical neoplastic, often pleomorphic cells that invade other tissues. "We firstly evaluated the DNA alterations of SOAT1 and SOAT2 in the Cancer Genome Atlas (TCGA) pan-cancers via cBioPortal." (PMID 34052835, 2021).
infection (3 papers, 2023 to 2025). The state of being infected such as from the introduction of a foreign agent such as serum, vaccine, antigenic substance or organism. "SOAT1−/− and SOAT2−/− cells dramatically reduced virus production by ~100-fold at 24 and 48 hours post-infection." (PMID 41306517, 2025). "CE-LD formation is mediated by Sterol O-acyltransferases 1 and 2 (SOAT1/SOAT2), whose activities were upregulated early during infection, coinciding with increased CE-LD formation and transition to liquid crystalline phases." (PMID 41256363, 2025). "To understand their respective roles in SARS-CoV-2 infection we transfected siRNAs either individually or in combination to knockdown (KD) SOAT1 and SOAT2 expression in VeroE6-TMPRSS2 or Calu-3 cells prior to infection." (PMID 37134108, 2023). "Similar to live infection, SOAT1−/− and SOAT2−/− cells had profoundly reduced prM and E levels." (PMID 41306517, 2025).
cardiovascular disease (1 paper, 2021). "In addition, there is little support for ACAT enzymes as a drug target for cardiovascular disease based on the lack of findings from SOAT1 and SOAT2 genome-wide association studies, and the absence of rare variants associated with relevant phenotypes." (PMID 34436484, 2021).
metabolic disorder (1 paper, 2025). "SOAT2 has been implicated in various metabolic disorders, such as atherosclerosis and non‐alcoholic fatty liver disease." (PMID 39588852, 2025).
SOAT2 also shares sentences with these, for which no sentence is quoted: Hepatic steatosis (2 papers); Hypercholesterolemia (2); acute myeloid leukemia (1); chylomicron retention disease (1); Cirrhosis (1); colorectal cancer (1); familial lipoprotein lipase deficiency (1); hyperglycaemia (1); liver cancer (1); melanoma (1); Renal insufficiency (1); type 1 diabetes (1); viral infection (1).